ALK (ALK receptor tyrosine kinase)
Diseases named in the same sentence as ALK in open-access papers (continued):
Sharing a sentence is not in itself a finding about the gene and the disease.
anaplastic large cell lymphoma (continued). "For anaplastic large cell lymphoma, the use of CD3 and other T-cell markers, as well as CD4, CD8, ALK, and CD30, is helpful for diagnosis." (PMID 37958219, 2023). "Anaplastic large cell lymphoma (ALCL), is a type of lymphoma that can be classified into two subtypes: ALK+ and ALK-." (PMID 37388733, 2023). "In the hematopoietic system, C/EBPβ is a pro-oncogenic factor in ALK-positive anaplastic large cell lymphoma (ALCL) as a crucial downstream target of oncogenic ALK-signalling." (PMID 35408476, 2022). "These two compounds efficiently induced the degradation of ALK in NSCLC, anaplastic large cell lymphoma (ALCL), and neuroblastoma (NB) cell lines." (PMID 36142231, 2022). "Anaplastic lymphoma kinase (ALK) is a receptor tyrosine kinase expressed at early stages of normal development and in various cancers including ALK-positive anaplastic large cell lymphoma (ALK+ ALCL), in which it is the main therapeutic target." (PMID 35211406, 2022). "In 1994, ALK was originally discovered in an anaplastic large cell lymphoma (ALCL) cell line, in which the ALK gene was fused with the nucleophosmin 1 (NPM1) gene, resulting in a new fusion protein, NPM‐ALK." (PMID 34845836, 2022). "According to the WHO Classification of Tumours of Haematopoietic and Lymphoid Tissues, there are four subtypes of anaplastic large cell lymphoma: ALK-positive ALCL (ALK+ALCL), ALK-negative ALCL (ALK−ALCL), primary cutaneous ALCL (pcALCL), and breast-implant-associated ALCL (BIA-ALCL)." (PMID 35406421, 2022). "The main physiologic aspect inhibited by the anaplastic lymphoma kinase (ALK) gene is brain development, which can keep many cancers altered, including non-small-cell lung cancer (NSCLC) or anaplastic large cell lymphomas (ALCL)." (PMID 35956900, 2022). "Anaplastic large cell lymphoma (ALCL), anaplastic lymphoma kinase (ALK)-positive is a T cell lymphoma consisting of large cells with an abundant cytoplasm and multiple nuclei that may resemble HRS cells (Hodgkin-like pattern)." (PMID 35454013, 2022). "First discovered in anaplastic large cell lymphoma (ALCL) as a driver translocation, ALK gene alterations have been described in several different tumors, including melanocytic neoplasms." (PMID 35747831, 2022). "In addition, Hoareau-Aveilla C. and colleagues studied its role in NPM-Anaplastic large cell lymphoma (NPM -ALK+ ALCL) cells, where it regulates the expression of cyclin E1, CDK6, and E2F3." (PMID 36498861, 2022). "In 2016, the World Health Organization (WHO) recognized four distinct entities of anaplastic large cell lymphoma (ALCL) including ALK-negative primary cutaneous ALCL, breast implant-associated ALCL, systemic ALK-negative (ALK(–)) or ALK-positive (ALK(+)) ALCL." (PMID 33466277, 2021). "A recent focused study on anaplastic large-cell lymphomas (ALCLs) expressing the oncogenic fusion kinase NPM-ALK, identified NPM-ALK targeted phosphorylation sites on nuclear interaction partner of ALK (NIPA) which promote lymphomagenesis when phosphorylated." (PMID 33923680, 2021). "The most common histologic type was extranodal NK/T-cell lymphoma, nasal type (ENKTL; 34.2%), followed by monomorphic epitheliotropic intestinal T-cell lymphoma (MEITL; 31.6%), intestinal T-cell lymphoma, NOS (ITCL, NOS, 18.4%), anaplastic large cell lymphoma, ALK-negative (ALCL, ALK-; 13.2%)." (PMID 34072328, 2021). "The major subtypes in children and adolescents are the mature B-cell lymphomas Burkitt lymphoma/leukemia (BL, B-AL, 45%) and diffuse large B-cell lymphomas (DLBCL, 10%), lymphoblastic lymphomas (LBL, 20%) and ALK-positive anaplastic large cell lymphomas (ALCL, 15%)." (PMID 33921029, 2021). "Initially discovered in anaplastic large cell lymphoma (ALCL), the ALK anaplastic lymphoma kinase is a tyrosine kinase which is affected in lymphomas by oncogenic translocations, mainly NPM-ALK." (PMID 33466277, 2021).
anaplastic large cell lymphoma (continued). "Anaplastic large cell lymphoma (ALCL), an aggressive CD30-positive T-cell lymphoma, comprises systemic anaplastic lymphoma kinase (ALK)-positive, and ALK-negative, primary cutaneous and breast implant-associated ALCL." (PMID 34552066, 2021). "Here, we examined the possibility that inhibition of an oncogenic kinase, anaplastic lymphoma kinase (ALK), might trigger ICD in anaplastic large cell lymphoma (ALCL) in which ALK is activated due to a chromosomal translocation." (PMID 34272360, 2021). "The differential diagnosis is broad and includes anaplastic large cell lymphoma (ALCL); EBV-positive DLBCL, NOS; PBL; HHV8-positive DLBCL, NOS; ALK-positive LBCL; and PM." (PMID 34572754, 2021). "In anaplastic large cell lymphoma (ALCL), ALK was originally characterized as a nucleophosmin fusion partner." (PMID 32664698, 2020). "Herein, we developed pH-responsive multifunctional DNA nanomicelles (DNMs) as delivery vehicles for controllable release of doxorubicin (Dox) and anaplastic lymphoma kinase (ALK)-specific siRNA for the chemo-gene synergetic therapy of anaplastic large cell lymphoma (ALCL)." (PMID 32724469, 2020). "In contrast, cytosolic ALK fusion proteins, such as NPM1-ALK and EML4-ALK, are constitutively active and common drivers of tumor progression in anaplastic large-cell lymphoma and non-small cell lung cancer." (PMID 32917927, 2020). "Anaplastic Large Cell Lymphoma (ALCL), ALK (Anaplastic Lymphoma Kinase) positive account for 1–3% of adult T-NHL but correspond to 15% of childhood lymphoma." (PMID 30704144, 2019). "ALK is a receptor tyrosine kinase that was first identified as a fusion gene with nucleophosmin 1 (NPM1-ALK), via a 2;5 chromosomal translocation in anaplastic large-cell lymphoma." (PMID 31278140, 2019). "Originally identified as a fusion gene in anaplastic large-cell lymphoma (ALCL), the function of native ALK is not fully understood." (PMID 29455675, 2018). "Anaplastic lymphoma kinase (ALK), a tyrosine kinase receptor, was found in anaplastic large-cell lymphoma (ALCL) cell lines in 1994 as a member of the insulin receptor superfamily which was closely associated with both solid and hematological tumors." (PMID 30680072, 2018). "Anaplastic large cell lymphoma (ALCL) is an aggressive T cell lymphoma characterized by cohesive proliferation of large pleomorphic lymphoma cells, abnormal activation of anaplastic lymphoma kinase (ALK) oncogene, and high-level expression of CD30 molecules." (PMID 30292138, 2018). "Within this rather rare disease group, the most common subtype is PTCL-not otherwise specified (NOS), which summarizes cases not attributable to other entities, followed by angioimmunoblastic T-cell lymphoma (AITL), ALK+ anaplastic large cell lymphoma (ALCL), and ALK− ALCL." (PMID 29148847, 2018). "Responses to crizotinib have also been reported in patients with anaplastic large-cell lymphoma (ALCL) and inflammatory myofibroblastic tumors, both of which have a high incidence of ALK rearrangements, especially in children." (PMID 28032129, 2017). "Anaplastic lymphoma kinase (ALK) is a receptor tyrosine kinase that was initially discovered and characterized in a rare type of lymphoma called anaplastic large-cell lymphoma (ALCL) as an NPM-ALK fusion protein." (PMID 29143801, 2017). "Chromosomal rearrangements involving the anaplastic lymphoma kinase (ALK) gene can occur in different cancers including NSCLC, anaplastic large cell lymphoma and inflammatory myofibroblastic tumors." (PMID 27045755, 2016). "In acute promyelocytic leukaemia (APL), anaplastic large cell lymphoma (ALCL), myelodysplastic syndrome (MDS) and acute myeloid leukaemia (AML), NPM is reported to form fusion proteins with ALK, RARα, and MLF15." (PMID 27619510, 2016). "It has been shown that the ALK fusion protein in NSCLC can be difficult to detect with the ALK1 antibody, which is used to diagnose anaplastic large cell lymphoma." (PMID 27769042, 2016).
anaplastic large cell lymphoma (continued). "AP-1 transcription factor was also identified as an ALK-regulated phosphoproteins, and AP-1 has been previously found to act downstream of NPM-ALK to promote cell-cycle progression in anaplastic large-cell lymphoma." (PMID 27732954, 2016). "The vast majority of anaplastic lymphoma kinase-positive anaplastic large cell lymphoma (ALK+ALCL) tumors express the characteristic oncogenic fusion protein NPM-ALK, which mediates tumorigenesis by exerting its constitutive tyrosine kinase activity on various substrates." (PMID 25978431, 2015). "Ring finger protein 213 (RNF213) has been reported as a fusion partner of ALK and MYC in anaplastic large cell lymphoma and inflammatory myofibroblastic tumor." (PMID 26089344, 2015). "Anaplastic lymphoma kinase (ALK) is a target molecule for the treatment of several cancers, including NSCLC, inflammatory myofibroblastic tumor, and anaplastic large-cell lymphoma." (PMID 26271036, 2015). "Not surprisingly, GzB is expressed in a number of T/NK cell neoplasms including anaplastic lymphoma kinase-positive, anaplastic large cell lymphoma (ALK+ ALCL), ALK- ALCL, and nasal-type NK/T cell lymphoma, as well as other lymphoid cancers including some Hodgkin lymphoma and multiple myeloma." (PMID 25168906, 2014). "Human immunodeficiency virus (HIV)-associated anaplastic large cell lymphoma (ALCL) is not so common, and anaplastic lymphoma kinase protein (ALK)-negative ALCL is rare and has a low survival rate." (PMID 24010049, 2013). "A similar strong response of a single agent was observed in ALK+-anaplastic large cell lymphoma (ALCL) patients treated with Crizotinib, an inhibitor of the ALK tyrosine kinase." (PMID 23431463, 2013). "Anaplastic lymphoma kinase (ALK) is a receptor tyrosine kinase that was discovered in anaplastic large-cell lymphoma (ALCL) in the form of a fusion protein, NPM-ALK." (PMID 22347464, 2012). "In Western countries nodal tumours are the most common form and include three main subtypes: PTCL, NOS, angioimmunoblastic T-cell lymphoma (AITL), and anaplastic large cell lymphoma (ALCL), anaplastic lymphoma kinase (ALK)-positive (ALCL, ALK+)." (PMID 21887344, 2011). "In contrast to HS, diffuse large B-cell lymphoma constantly express various pan-B markers such as CD19, CD20, CD22, and CD79a, while anaplastic large cell lymphomas are positive for CD30, and ALK." (PMID 17324277, 2007). "IHC analysis of Tissue Micro Arrays (TMAs) revealed high UMG1 expression in 62.3% of TCL samples, including peripheral T-cell lymphoma-not otherwise specified (PTCL-NOS) and ALK-negative anaplastic large cell lymphoma (ALCL)." (PMID 41834433, 2026). "ALK-negative primary anaplastic large cell lymphoma (ALCL) of the small intestine is exceptionally rare and presents significant diagnostic and therapeutic challenges." (PMID 41395560, 2025). "In their study, researchers identified a high proportion (≥15%) of activated CTLs in biopsy specimens from patients with Hodgkin’s disease and ALK-negative anaplastic large cell lymphoma (ALCL), which correlated with poorer OS and PFS." (PMID 41567188, 2025). "Reactivation of the ancient LTR was found to promote a novel oncogenic transcript of ERBB4 in ALK-negative anaplastic large cell lymphoma (ALCL)." (PMID 41459148, 2025). "Nevertheless, for patients with NPM-ALK-positive subtypes, two targeted therapeutic approaches are available: one involves the use of an ALK inhibitor, while the other targets CD30, a surface marker molecule that is highly expressed on anaplastic large-cell lymphoma cells." (PMID 40584293, 2025). "The management of gastrointestinal ALK-negative anaplastic large cell lymphoma remains challenging, with CHOP (cyclophosphamide, doxorubicin, vincristine, prednisone) chemotherapy serving as the historical standard regimen." (PMID 41395560, 2025).
anaplastic large cell lymphoma (continued). "At Age 6, he presented with cervical lymphadenopathy and general symptoms, leading to a diagnosis of ALK-negative anaplastic large-cell lymphoma, Stage II." (PMID 40641635, 2025). "Based on radiological, histomorphological, and immunohistochemical findings, a diagnosis of primary ALK-negative anaplastic large cell lymphoma of the jejunum was established." (PMID 41395560, 2025). "It has been found that ALK is the primary marker applied for diagnosing and predicting tumors in T-cell lymphomas using liquid biopsy, demonstrating the significance of MRD application for anaplastic large cell lymphoma." (PMID 38365716, 2024). "The anaplastic lymphoma kinase (ALK) receptor tyrosine kinase plays a pivotal role in cellular development, and alterations in the ALK gene may occur in cancers such as anaplastic large cell lymphoma, neuroblastoma, and NSCLC." (PMID 38474400, 2024). "A diagnosis of EBV positive large B cell lymphoma rather than ALK negative anaplastic large cell lymphoma or T cell lymphomas was rendered." (PMID 39055348, 2024). "Crizotinib is an ALK and ROS1 inhibitor approved for NSCLC and anaplastic large cell lymphoma." (PMID 38345654, 2024). "More recent literature has identified rearrangements of the DUSP22-IRF4 locus in a small subset of lymphomatoid papulosis cases, originally described as a characteristic of nodal ALK-negative anaplastic large cell lymphoma." (PMID 38835967, 2024). "Eight cases (15%) were T-cell lymphomas and all of them were anaplastic large-cell lymphomas (ALCLs), in particular anaplastic lymphoma kinase (ALK)-negative cases, while for two cases the ALK status was not reported." (PMID 39682271, 2024). "Our study demonstrates that our 5A4-based protocol is non-inferior to the ALK01 antibody for the diagnosis of ALK-positive anaplastic large cell lymphoma, thus allowing our laboratory to discontinue the use of the ALK01-based protocol." (PMID 38175372, 2023). "The differential diagnosis between ALK-negative anaplastic large cell lymphoma (ALK- ALCL) and peripheral T-cell lymphoma, not otherwise specified (PTCL, NOS) with high expression of CD30 (CD30high) are essential." (PMID 37388733, 2023). "A genetic subtype of systemic ALK-negative anaplastic large-cell lymphoma known as DUSP22-rearranged ALCL has been identified, carrying a relatively better prognosis." (PMID 37762472, 2023). "Anaplastic large cell lymphoma (ALCL) is a type of non-Hodgkin lymphoma (NHL) that is characterized by a neoplastic proliferation of CD30+ lymphoid cells, with frequent expression of anaplastic lymphoma kinase (ALK)." (PMID 37275877, 2023). "Histologic examination of the right axillary nodule revealed anaplastic large-cell lymphoma that was ALK negative and CD30 positive." (PMID 36676781, 2023). "An anaplastic large cell lymphoma (ALCL) that does not express detectable amounts of the ALK protein is known as an ALK− anaplastic large cell lymphoma (ALCL)." (PMID 37443818, 2023). "Anaplastic lymphoma kinase (ALK)-negative anaplastic large-cell lymphoma (ALCL) is highly malignant in nature." (PMID 37568787, 2023). "To compare the two protocols, we stained tissue microarrays of 126 hematolymphoid neoplasms and an additional 21 primary cutaneous ALK-negative anaplastic large cell lymphomas with both protocols." (PMID 38175372, 2023). "The study enrolled 12 patients, 6 with angioimmunoblastic T cell lymphoma (AITL), 3 with PTCL-NOS, and one patient each with anaplastic lymphoma kinase negative anaplastic large cell lymphoma (ALK-ALCL), enteropathy associated T cell lymphoma and hepatosplenic gamma delta T cell lymphoma." (PMID 36959853, 2023). "Re-biopsy ultimately revealed an anaplastic lymphoma kinase (ALK)-negative anaplastic large cell lymphoma (ALCL), but his disease initially showed a remarkable response to MEK inhibition." (PMID 35494913, 2022).
anaplastic large cell lymphoma (continued). "Nevertheless, DUSP22 rearrangements present not only in ALK-negative anaplastic large cell lymphoma, but also in primary cutaneous anaplastic large cell lymphoma and lymphomatoid papulosis." (PMID 35406421, 2022). "Ultrasound-guided biopsy of right breast mass and right axillary lymph node showed CD 30-positive ALK-negative anaplastic large cell lymphoma, and staging work up showed extension of the tumor to chest wall and ribs consistent with advanced disease." (PMID 35721802, 2022). "Declined expression of DUSP22 in t cell lymphomas has been discovered, which suggests that this phosphatase plays a role similar to a tumor suppressor gene in ALK-negative anaplastic large cell lymphomas." (PMID 35406421, 2022). "Of six anaplastic large cell lymphoma patients, five were ALK positive, and we saw only one case of ALK-negative anaplastic large cell lymphoma." (PMID 35784957, 2022). "Similar to ALK-positive anaplastic large cell lymphoma, the clonal rearrangements of the T cell receptor genes can be detected in most ALK-negative anaplastic large cell lymphoma cases." (PMID 35406421, 2022). "In addition to the good prognosis of anaplastic lymphoma kinase positive anaplastic large cell lymphoma (ALK + ALCL), the other PTCL subtypes have poor response to chemotherapy and are prone to relapse, and the long-term survival rate is less than 30%, which is significantly worse than B-NHL2–4." (PMID 35999255, 2022). "In addition, in ALK-ALCL (anaplastic large cell lymphoma), snoRNA U3 can distinguish ALK+ from ALK-ALCL samples and might serve as an independent diagnostic marker." (PMID 36033520, 2022). "Most patients with ALK-negative anaplastic large cell lymphoma are adults aged between 40 and 65, with males being slightly more prone to developing the disease than females (M:F ratio 1.5:1)." (PMID 35406421, 2022). "Nodal PTCLs include ALK-positive and ALK-negative anaplastic large cell lymphoma; nodal T-cell lymphoma with T follicular helper cell origin; and PTCL, not otherwise specified." (PMID 36010351, 2022). "Other studies on anaplastic large cell lymphoma, the most common T-cell NHL in children, found that tumor progression was primarily driven by a fusion product between ALK and mainly nucleophosmin 1 (NPM1) called NPM-ALK." (PMID 36172151, 2022). "The following percutaneous biopsy of the mass demonstrated a proliferation of phenotypically aberrant population of large cells that expressed CD30 and CD45, negative for CD3, CD20, and ALK1, diagnostic for anaplastic large cell lymphoma, ALK-negative (ALK-ALCL)." (PMID 36703782, 2022). "The main learning point from this report is that these tumors can present atypically even in adults and can be ALK-1 negative, which is contrary to the typical systematic anaplastic large-cell lymphomas that are positive for ALK." (PMID 34900354, 2021). "For example, in the case of diffuse large B-cell lymphoma (DLBCL) and anaplastic large cell lymphoma (ALCL), pediatric patients are more likely to have GCB disease (a main subtype of DLBCL) and anaplastic lymphoma kinase (+) ALCL (ALK+ ALCL), both of which have superior prognostic features of NHL." (PMID 34631756, 2021). "It is unlike the more common ALK-positive anaplastic large cell lymphoma, although the latter shares the ALK rearrangement pathognomonic for this entity." (PMID 34513457, 2021). "In addition, PTPN1 and PTPN2 have been shown to dephosphorylate ALK and PTPN11 in anaplastic large cell lymphomas, and gene deletion of either PTPN1 or PTPN2 induced resistance to ALK inhibitors." (PMID 34957126, 2021). "The number of SNV/Indel in anaplastic large cell lymphoma, ALK-positive was significantly lower than that in anaplastic large cell lymphoma, ALK-negative (P = 0.049)." (PMID 34461835, 2021). "ALK-negative anaplastic large cell lymphoma is a rare T-cell neoplasm with an aggressive course requiring prompt diagnostic work-up and treatment." (PMID 32509362, 2020).